TAFA5 (TAFA chemokine like family member 5)
Description:
Acts as a chemokine-like protein by regulating cell proliferation and migration through activation of G protein-coupled receptors (GPCRs), such as S1PR2 and FPR2 (By similarity). Stimulates chemotactic migration of macrophages mediated by the MAPK3/ERK1 and AKT1 pathway (By similarity). Blocks TNFSF11/RANKL-induced osteoclast formation from macrophages by inhibiting up-regulation of osteoclast fusogenic and differentiation genes (By similarity). Stimulation of macrophage migration and inhibition of osteoclast formation is mediated via GPCR FPR2 (By similarity). Acts as an adipokine by negatively regulating vascular smooth muscle cell (VSMC) proliferation and migration in response to platelet-derived growth factor stimulation via GPCR S1PR2 and G protein GNA12/GNA13-transmitted RHOA signaling (By similarity). Inhibits injury-induced cell proliferation and neointima formation in the femoral arteries (By similarity).
Synonyms: FAM19A5; TAFA-5; QLLK5208; UNQ5208
Tractability: Antibody: UniProt places it where antibodies can reach, with high confidence; UniProt predicts a signal peptide or a membrane-spanning region; its Gene Ontology location is reachable by antibodies, with medium confidence.
Gene: Protein-coding gene on chromosome 22 (48,489,431 to 48,850,912, forward strand). Ensembl gene ENSG00000219438.
Subcellular location: Secreted
Gene Ontology:
Molecular function: G protein-coupled receptor binding; receptor ligand activity
Biological process: G protein-coupled receptor signaling pathway; negative regulation of vascular associated smooth muscle cell proliferation
Cellular component: extracellular region; cytoplasm
Genetic constraint (gnomAD): Loss-of-function variants: 4 observed, 11.16 expected, observed/expected ratio (o/e) 0.36, 90% interval 0.18 to 0.82. The synonymous counts are far from expectation, so gnomAD's model fits this gene poorly and the ratio says little. Missense variants: 151 observed, 163.68 expected, observed/expected ratio (o/e) 0.92, 90% interval 0.81 to 1.06. Synonymous variants: 97 observed, 71.48 expected, observed/expected ratio (o/e) 1.36, 90% interval 1.15 to 1.61.
Homologues: Orthologues: chimpanzee TAFA5 (99% identical), mouse Tafa5 (99% identical), rat Tafa5 (99% identical), pig TAFA5 (98% identical), dog TAFA5 (92% identical), zebrafish tafa5a (77% identical), guinea pig TAFA5 (75% identical), tropical clawed frog tafa5 (67% identical), zebrafish tafa5b (64% identical), macaque TAFA5 (48% identical).
Diseases named in the same sentence as TAFA5 in open-access papers:
TAFA5 is named in the same sentence as 42 diseases in open-access papers, as found by Europe PMC text mining. Sharing a sentence is not in itself a finding about the gene and the disease. The quoted sentences say what the papers report.
Obesity (7 papers, 2020 to 2024). Accumulation of substantial excess body fat. "TAFA5, also known as FAM19A5, plays a protective role in atherosclerosis, obesity and inflammation." (PMID 36230385, 2022).
depression (6 papers, 2021 to 2025). "Dlgap1, Trank1, and Tafa5 are established risk genes for neuropsychiatric diseases, with Dlgap1 specifically related to major depressive disorder, Trank1 associated with bipolar disorder, and Tafa5 linked to depressive-like behaviors." (PMID 39272155, 2024). "In mice, the TAFA5 gene was associated with depression and was expressed in brain tissue." (PMID 39062924, 2024). "TAFA5 has recently been implicated in the progression of cognitive impairment in vascular dementia patients and could be a vital regulator of depression." (PMID 35712659, 2022). "Together, these findings indicate TAFA5 could be a critical regulator of cognitive function and warrants further research of its potential for diagnosis and treatment-based approaches of depression." (PMID 35712659, 2022). "With the exception of TAFA5, none of these genes have previously been associated with depression." (PMID 39062924, 2024).
breast carcinoma (2 papers, 2021 to 2022). "The expression of FAM19A5, also known as TAFA5, is influenced by the activation of β-catenin and c-Myc promotes the Wnt/β-catenin activity in breast cancers." (PMID 33047283, 2021).
gastric cancer (2 papers, 2020 to 2022). A primary or metastatic malignant neoplasm involving the stomach. "Overexpression of TAFA5 in gastric cancer was associated with poor differentiation, tumour progression, nodal, and metastasis stages." (PMID 35712659, 2022). "TAFA5 was upregulated in gastric cancer cells compared with normal cells, which is correlated with unfavourable patient prognoses." (PMID 35712659, 2022). "Interestingly, TAFA5 expression was significantly correlated with genes found to be associated with epithelialmesenchymal transition, which is suggestive of TAFA5 involvement in the progression of gastric cancer." (PMID 35712659, 2022). "In vitro findings showed that downregulation of TAFA5 could inhibit the proliferation and migration of gastric cancer cell lines." (PMID 35712659, 2022).
Stroke (2 papers, 2010 to 2022). Sudden impairment of blood flow to a part of the brain due to occlusion or rupture of an artery to the brain. "FAM19a5 has been proposed to regulate brain fluid balance, and elevated levels of TAFA5 may thus help to control cerebral edema after stroke." (PMID 20509949, 2010).
cardiac hypertrophy (1 paper, 2023). "Candidate gene identification analyses of exercise-induced cardiac hypertrophy identified five potential regulatory transcripts: IL31ra, Fam167b, Tafa5, Crip3, and Nanos1 (p < 0.01)." (PMID 37178122, 2023).
tumour (3 papers, 2016 to 2024). "In addition, previous studies have found that TAFA5 was associated with DNA copy number alterations in gliomas but its role of in tumour development requires further investigation." (PMID 35712659, 2022).
cancer (2 papers, 2023 to 2024). A tumor composed of atypical neoplastic, often pleomorphic cells that invade other tissues. "However, as a member of the TAFA family, TAFA5 can encode small secretory proteins in the central nervous system and has been shown to increase expression in human malignant tumors." (PMID 37895309, 2023).
TAFA5 also shares sentences with these, for which no sentence is quoted: neurological diseases (4 papers); Alzheimer disease (3); Cognitive impairment (3); degenerative disease (3); psychiatric diseases (3); atherosclerosis (2); bone disorder (2); brain injury (2); cardiovascular disease (2); cholangiocarcinoma (2); metabolic disease (2); vascular dementia (2); Anorexia (1); Anxiety (1); autism (1); bipolar disorder (1); cerebral infarction (1); cerebral small vessel disease (1); cognitive decline (1); colorectal cancer (1); Constipation (1); glioma (1); head and neck squamous cell carcinoma (1); infection (1); liver cancer (1); mantle cell lymphoma (1); memory impairment (1); neurodevelopmental disorder (1); neuromyelitis optica spectrum disorders (1); nonalcoholic fatty liver disease (1).
A further 4 diseases each share a sentence with TAFA5 in 1 paper.